FTL (ferritin light chain)
Diseases named in the same sentence as FTL in open-access papers (continued):
Sharing a sentence is not in itself a finding about the gene and the disease.
tumor (continued). "To this end, we analyzed datasets from The Cancer Genome Atlas (TCGA), a landmark cancer genomics database started in 2006, and additionally employed a number of bioinformatics tools to assess the relationship between tumor FTL and FTH1 levels and tumor infiltration by various immune cell subsets." (PMID 33864445, 2021). "FTH and FTL were expressed by tumor cells and cells with microglial/macrophage morphology." (PMID 28837569, 2017). "We found that TfR1, FTH, and FTL were expressed by tumor cells in all grades." (PMID 28837569, 2017). "Multivariate analysis for patients with GBMs (n = 70) with TfR1, FTH, and FTL tumor cell score." (PMID 28837569, 2017). "Considering that hypoxia‐inducible factor (HIF)‐1α drives the resistance of tumor cells to ferroptosis and CDCP1 is a downstream target gene of the HIF‐1/2 pathway, we speculate that the hypoxic TME may be associated with CDCP1+FTL+ CAFs." (PMID 40019403, 2025). "However, the role played by ferritin in regulating the tumor microenvironment is unclear, and little is known about whether or how FTL and FTH1 expression levels might correlate with tumor infiltration by diverse immune cell subsets." (PMID 33864445, 2021). "To exclude the possibility that the observed differential expression of FTL was caused by differences in microvessel densities between SQCLC and HNSCC, we performed CD34 staining, which confirmed similar microvessel densities in the two tumour types (Fig EV2C)." (PMID 30097507, 2018). "Comparingtumor with corresponding control samples revealed 221 differentiallyexpressed proteins (FDR < 0.05) with FTL, PCOLCE, and RCN3 beingmost striking in tumor tissue." (PMID 40574313, 2025). "Consistently, we also found the colocalization of WTX-L with SLC7A11 and FTL, suggesting that WTX as a regulator of ferroptosis is prevalent in tumor development." (PMID 40109379, 2025). "Corresponding with FTL expression in MOFA2 latent factor 2, more moTAM were in hypoxic area 9 than the surrounding tumor." (PMID 38123840, 2024). "BECN1, ELAVL1, and ATG16L1 were highly expressed in tumor tissues, while NCOA4, FTH1, FTL, SNCA, TNF, ATG7, and ZFP36 showed low expression levels." (PMID 39593730, 2024). "The increased demand for iron in tumor cells leads to elevated levels of TFR1 and ferritin light chain (FTL)." (PMID 39045454, 2024). "FTL inhibition reprogrammed the immune microenvironment by triggering the activation of CD8+ T cells, thus enhancing anti-tumor immunity." (PMID 37441589, 2023). "The expression of all six FRGs was significantly different (p < 0.05), with FTH1, FTL, and PCBP1 being overexpressed in the tumor group and ZFP36, NCOA4, and TNF expressed less in the tumor group." (PMID 37555866, 2023). "In the present study, we found that expressions of FTL and FTH1 correlated positively with levels of the immune checkpoint proteins TIM-3 and LAIR1, both of which can suppress tumor immunity." (PMID 33864445, 2021). "To determine the source(s) of the correlation between FTL and FTH1 levels and Immune Score in most cancers, we examined correlations between expression and tumor-infiltrating cell subsets using MCP-counter, TIMER, and TIMINER." (PMID 33864445, 2021). "For FTL, FTH, and IRP2, we found an increased mRNA expression in lower tumor grades (G1-G2) and lower tumor pT-stage (pT1–pT2), but either similar or lower expression within the group of higher tumor grades (G3-G4) and higher tumor pT-stage (pT3–pT4)." (PMID 32106629, 2020). "Ovarian cancer samples had elevated FTL and FTH1 detected in the cytoplasm and nucleus compared to benign tissue and increased with tumor grade." (PMID 32328462, 2020). "In a number of studies, the expression of different iron-regulated genes such as TfR, FTL, and IRP2 in tumor cells was correlated with a poor prognosis and a higher tumor grade, leading to increased chemoresistance in cancer patients." (PMID 31083487, 2019).
tumor (continued). "Tumor ferritins are composed of different ratios of the two functionally distinct ferritin subunits, FTH and FTL." (PMID 26871431, 2016). "ESCC tissue microarray (TMA) containing tumor vs non-tumor tissues of ESCC specimens was applied to validate the expression and clinical association of FTL in ESCC." (PMID 41281761, 2025). "Interestingly, immunomodulatory proteins such as CSF-1, CCL2, FTH, FTL, and TGF-β chemokines have been identified in tumor exosomes." (PMID 39008536, 2024). "Likewise, LASS2 overexpression reversed the changes in the levels of FTH1, FTL and GPX4 induced by either Fer-1 or erastin in these tumour cell lines." (PMID 38419028, 2024). "Among the fourteen ferritinophagy-related genes studied, ten exhibited significant differences between tumor and normal samples: NCOA4, FTH1, FTL, SNCA (all p < 0.0001), BECN1 (p = 0.031), ELAVL1 (p = 0.00023), TNF (p = 0.00074), ATG16L1, ATG7, and ZFP36 (all p < 0.0001)." (PMID 39593730, 2024). "Importantly, tumoral c-Jun expression was positively correlated with SOX9, SOX2, OCT4, FTH1, FTL and TFRC expression in consecutive PDAC tumour tissues." (PMID 37143164, 2023). "Using the TCGA and GTEx data, we could learn the expression of five genes of the TEXPM construct, FTL, GZMA, CD14, and NPC2 were highly expressed in tumor tissues, and IER3 was highly expressed in paracancerous tissues." (PMID 37354485, 2023). "We speculate that FTL and FTH1 may influence TIM-3 and LAIR levels by affecting immune cell infiltration into the tumor." (PMID 33864445, 2021). "Apparently, the expression of different iron-regulated genes such as the transferrin receptor (TfR1), ferritin light chain (FTL), and the iron regulatory protein (IRP)-2 in tumor cells correlated with a poor prognosis, a higher tumor grade, and increased chemoresistance." (PMID 30641920, 2019). "Further, implanting BTICs in mice containing FTH or FTL knockdown resulted in sparse or absent tumor formation." (PMID 28837569, 2017). "Both, FTL and S100A9 are increased in serum under inflammatory conditions, and they might thus represent tumour-related inflammatory responses." (PMID 25177240, 2014). "Overexpression of FTL, GPX4 and NUPR1 in UCA1+ EPCAM+ cells suggests these key genes may be upregulated further along the RMC oncogenic program to increase protection of the tumor against cell death induced by ferroptosis." (PMID 35837094, 2022). "Tumor cells increase iron uptake through the upregulation of divalent metal transporter-1 (DMT1), transferrin/transferrin-receptor (Tf/TfR), and lipocalin-2/lipocalin-2receptor (Lcn-2/Lcn-2R) systems, and its storage by ferritin (FT) heavy chain (FTH) and FTL overexpression." (PMID 32426284, 2020). "Moreover, the expression of different iron-regulated genes such as transferrin receptor (TfR), ferritin light (FTL), and the iron regulatory protein (IRP)-2 in tumor cells was correlated with a poor prognosis and a higher tumor grade, leading to increased chemoresistance." (PMID 27806101, 2016). "Additionally, FTL and FTH1 bind the anti-angiogenic molecule high molecular weight kininogen (HKa), preventing its dimerization, necessary for its functional activity and consequently, promoting endothelial cell survival, migration, adhesion, and angiogenesis to support tumor growth." (PMID 32328462, 2020). "Ferroptosis was found to be a shared specific pathway between ESCC and adjacent non-tumor tissue, as well as between ESCC lymph node metastasis and adjacent non-tumor tissue, of which FTL was selected as the pivotal target gene within this common pathway." (PMID 41281761, 2025). "We observed that VPA effectively blocked the transcription of FTL, FTH1 and NQO1 in tumor tissues, with or without Erastin treatment, and DFS treatment didn't affect the function of VPA." (PMID 40963919, 2025). "No grade-dependent increase was found for the tumor cell expression of FTH and FTL, but the expression level of FTL by microglia was highest in GBMs." (PMID 28837569, 2017).
cancer (44 papers, 2008 to 2025). A tumor composed of atypical neoplastic, often pleomorphic cells that invade other tissues. "The transition areas (II) that encompass both cancer cells and immune cells as defined in the original study exhibit high expression of FTL, CTSB, and HLA-associated genes (e.g., HLA-A, HLA-B, HLA-C), indicating immune infiltration in the TME." (PMID 40033360, 2025). "In recent years, an increasing number of investigations have demonstrated the tight association between FTL and malignant tumors." (PMID 37354485, 2023). "We then selected cancers in which FTL and FTH1 levels were associated with OS at P < 0.001, and performed Kaplan–Meier analysis of OS in patients stratified into high and low expression groups by ROC curve analysis." (PMID 33864445, 2021). "FTL expression was significantly associated with PFI in four cancer types: LGG (HR 1.5, 95% CI 1.26–1.78, P = 3.8 × 10−6), KIRC (HR 1.31, 95% CI 1.06–1.62, P = 1.4 × 10−2), UCEC (HR 1.21, 95% CI 1.00–1.46, P = 4.4 × 10−2), and GBM (HR 1.26, 95% CI 1.02–1.57, P = 3.3 × 10−2)." (PMID 33864445, 2021). "FTL is an inflammation marker also implicated in cancer, S100A9 is an important member of the Ca2+ signaling cascade reported to be altered in GBM tissue, and CNDP1 has been reported for its role in the regulation of the levels of carnosine, implicated as a potential drug for GBM." (PMID 23029420, 2012). "Lipid peroxidation MDA assay also displayed that when NCOA4 was overexpressed, cancer cells had more resistance to erastin-induced ferroptosis compared with only FTL overexpressed group." (PMID 41281761, 2025). "Iron (Fe2+) ferrous ions assay showed that when FTL was overexpressed, cancer cells would be more resistant to erastin-induced ferroptosis." (PMID 41281761, 2025). "Lipid peroxidation Malondialdehyde (MDA) assay also displayed that when FTL was knocked down, the ferroptosis of cancer cells would release more lipid oxidation." (PMID 41281761, 2025). "Iron (Fe2+) ferrous ions assay showed that when NRF2 was knocked down, cancer cells had similar resistance to erastin-induced ferroptosis compared with FTL overexpressed group." (PMID 41281761, 2025). "FTL expression in various ESCC cell lines was first predicted by Cancer Cell Line Encyclopedia, electrophoresis, and then detected by qPCR, western blot analysis." (PMID 41281761, 2025). "Iron (Fe2+) ferrous ions assay showed that when NCOA4 was overexpressed, cancer cells were more resistant to erastin-induced ferroptosis compared with only FTL overexpressed group." (PMID 41281761, 2025). "We further demonstrated that PDAC patients with the elevated proportion of CDCP1+FTL+ CAFs in TME suffered from advanced cancer stage, distant metastasis, and poor outcomes." (PMID 40019403, 2025). "In recent years, studies have found that FTL is closely related to the occurrence and progression in many cancers except for ESCC." (PMID 41281761, 2025). "Lipid peroxidation MDA assay also displayed that when NRF2 was knocked down, cancer cells had similar resistance to erastin-induced ferroptosis compared with FTL overexpressed group." (PMID 41281761, 2025). "Studies have demonstrated that oxidative stress response proteins, including Nrf2, can activate FTH1 and FTL in cancer cells, reducing free iron in the labile iron pool (LIP) and inhibiting ferroptosis." (PMID 40530331, 2025). "Lipid peroxidation MDA assay also displayed that when FTL was overexpressed, erastin-induced ferroptosis of cancer cells would release less lipid oxidation." (PMID 41281761, 2025). "Iron (Fe2+) ferrous ions assay showed that when FTL was knocked down, cancer cells would be more sensitive to erastin-induced ferroptosis." (PMID 41281761, 2025). "Both IRP1 and IRP2 exhibit tissue-specific expression and regulate FTH and FTL in a context-dependent manner in various cancers." (PMID 39852175, 2025).
cancer (continued). "Taken together, these findings suggested that NRF2 reversed overexpressed FTL function of enhancing cancer development and slightly affects ferroptosis in ESCC." (PMID 41281761, 2025). "To further evaluate the expression of FTL in human various cancers, we used the TIMER database for analysis." (PMID 41281761, 2025). "Several genes, including the transferrin receptor, ferritin heavy chain, ferritin light chain, iron exporter ferroportin, iron regulatory protein 2, and LCN2, have been implicated in the regulation of iron in cancer cells." (PMID 39850877, 2024). "The results showed that FTL was upregulated in 21 of the 27 cancers analyzed (77.8%), downregulated in three cancers (11.1%; CHOL, LAML, LUSC), and not significantly changed in three cancers (11.1%; BLCA, KICH, KIRP) compared with normal tissues." (PMID 33864445, 2021). "As was observed for OS, poor PFI was significantly associated with high FTL or high FTH1 mRNA levels in some cancers." (PMID 33864445, 2021). "In the present study, we found that FTL is upregulated in most of the 27 cancers examined, which is consistent with findings in other cancers and is likely related to the essential role of ferritin in cell proliferation." (PMID 33864445, 2021). "We found that FTL levels were positively related to PD-1 in 14/32 cancers (43.8%), PD-L1 in 10/32 (31.3%), CTLA4 in 13/32 (40.6%), TIM-3 in 26/32 (81.3%), LAG3 in 13/32 (40.6%), and LAIR1 in 26/32 (81.3%)." (PMID 33864445, 2021). "Hemopexin was expressed in the cancer-cell cytoplasm and in stromal fibroblasts (B), FTL expression was localized in the same location as hemopexin (not shown here)." (PMID 32663208, 2020). "FTL gathered in cancer lesions to promote proliferation is potentially taken up from plasma via specific receptors, such as scavenger receptor class A member-5 (SCARA5) from the release of TAMs, particularly in response to pro-inflammatory cytokines." (PMID 30591630, 2018). "Cluster 4 contained only 3 transcripts, composed of ferritin light chain (FLT) and ferritin heavy chain (FTH1), which have been associated with several cancers." (PMID 28957348, 2017). "As the results above showed that NRF2 reversed overexpressed FTL function of enhancing cancer development, we further explored whether it could reverse FTL promoting metastasis." (PMID 41281761, 2025). "Additionally, FTL silencing inhibits cancer cell growth, viability, and proliferation; reduces cancer cell survival, migration, and invasion; and increases apoptosis." (PMID 37834160, 2023). "A decreased IRP2 level or inactivated IRP1 would subsequently induce translational activation of ferritin Consistently, Western blot analysis showed that esophageal CSCs had higher levels of ferritin heavy chain (FTH) and ferritin light chain (FTL) compared with bulk cancer cells." (PMID 35053196, 2021). "Moreover, our analyses revealed positive associations between FTL and FTH1 expressions and infiltration of both cell types in most cancers." (PMID 33864445, 2021). "It was revealed that FTL could be used as a biomarker to discriminate benign and malignant tumors, and to predict the prognosis of patients with tumors." (PMID 32677981, 2020). "Hemopexin and FTL were mainly expressed in the cancer-cell cytoplasm and stromal fibroblasts." (PMID 32663208, 2020). "Besides, FTL was found to be overexpressed in various malignant tumors, and played a crucial role in regulating malignancy progress of cancers." (PMID 32677981, 2020). "Ferritin light chain was shown previously to be enriched in autophagosomal fractions from cancer cell lines as was calcium-binding and coiled-coil domain-containing protein 2, optineurin, autophagy-related protein 9A, all of which were also identified in this study." (PMID 26258666, 2015). "Additionally genes DPYD, ABCC1, FTL and ICAM3 whose expression is shown to be associated with outcome of cancer treatment were also observed in the data set." (PMID 18782426, 2008).
cancer (continued). "Time-dependent reductions in FTL (ferritin light chain) and FTH (ferritin heavy chain) protein levels were also found following QUE treatment in various cancer types." (PMID 38674891, 2024). "Another oncogene overexpressed in various malignant tumors, such as GBM cells and serum and CRC tissues and cell lines, ferritin light chain (FTL), interacts with PI3K/Akt, GADD45/JNK, TGF-β signaling, and cell cycle proteins." (PMID 37834160, 2023). "The fourth group, which was consistently identified as cancer by SRS images, contained highly expressed OSCC marker genes including GSTP1, AKR1B10, FTH1, and FTL." (PMID 35776767, 2022). "We also showed that FTL expression is positively related to poor prognosis in seven cancers, particularly LGG, and that FTL expression is elevated significantly in six of those cancers." (PMID 33864445, 2021). "In contrast to FTL, FTH1 expression was downregulated in 22 and upregulated in four of the 27 cancers examined in our study." (PMID 33864445, 2021). "The results suggested that high FTL or high FTH1 mRNA levels were each related to poor OS in several cancer types." (PMID 33864445, 2021). "We found that FTL and FTH1 are upregulated and downregulated, respectively, in most of the human cancers analyzed." (PMID 33864445, 2021). "Also, when FTL was overexpressed, H2O2-treated cancer cells would release less lipid oxidation, while the difference between the two groups was less than that of erastin-induced ferroptosis in mEC2 cells." (PMID 41281761, 2025). "To confirm whether FTL was one of the key genes for cancer development and ferroptosis in ESCC, we silenced FTL expression using shRNAs against FTL in ESCC cell lines (shb and shd)." (PMID 41281761, 2025). "Curcumin has been proven to modulate TFR1 levels, as well as the two subunits of FT, in cancer cells, ferritin heavy chain (FTH1) and ferritin light chain (FTL), which in turn influences intracellular iron transport and storage functions and alters labile iron levels." (PMID 39309443, 2024). "In fact, cancer cells are characterized by elevated iron content due to a deregulation of iron-related proteins such Transferrin Receptor1 (TfR1), Hepcidin, Ferroportin (FPN) and Ferritins (FtH and FtL, essential for iron storage)." (PMID 36764998, 2023). "Finally, the present study shows that both FTL and FTH1 levels are positively correlated with Tregs infiltration in most cancers." (PMID 33864445, 2021). "To determine whether FTL and FTH1 are differentially expressed in human cancers, we examined expression datasets from TCGA and GTEx databases." (PMID 33864445, 2021). "Nuclear factor erythroid 2-like 2 (NRF2) and myeloid zinc finger-1 (MZF-1) could impact cancer cell growth by transcriptionally regulating FPN, FTH, and FTL expression in prostate and breast cancer." (PMID 30591630, 2018). "Another important factor in this study was the fact that the cells were treated at confluence for a relatively long time (48 h), and this condition may contribute to the modulation of the expression of at least FTH1, FTL, and TFRC if compared with cells in active proliferation, such as cancer cells." (PMID 41303636, 2025). "Interestingly, TIM-3 was positively related to FTL and FTH1 in the most cancers, so does LAIR1." (PMID 33864445, 2021). "Notably, it has been demonstrated that only FTH, and not FTL, is directed towards cancer cells." (PMID 39852175, 2025). "Hence, regulating pathways involved in CDKN2A-associated genes or designing novel metal-based anticancer agents to induce ferroptosis and cuproptosis may guide us to develop new anti-cancer treatment strategies for BRCA, especially for the patients in the FTL-dominant subtype." (PMID 36052076, 2022). "TIMER analysis revealed that FTL expression and CD4+ T cells were positively correlated in 11/31 (35.5%) cancers, negatively correlated in 2/31 (6.5%), and was not correlated in 18/31 (58.1%)." (PMID 33864445, 2021).